VCP (valosin containing protein)
Diseases named in the same sentence as VCP in open-access papers (continued):
Sharing a sentence is not in itself a finding about the gene and the disease.
glaucoma (4 papers, 2016 to 2022). Increased pressure in the eyeball due to obstruction of the outflow of aqueous humor. "It is notable that VCP is highly expressed in all types of retinal neuronal cells, including retinal ganglion cells, which are lost in glaucoma." (PMID 27441270, 2016). "We propose “ATP maintenance” via inhibition of ATPase activities of VCP as a promising new neuroprotective strategy for currently incurable eye diseases, such as glaucoma." (PMID 27441270, 2016). "We have previously shown that Kyoto University Substances (KUSs), valosin-containing protein (VCP) modulators, suppress cell death in retinal ganglion cells of glaucoma mouse models through alterations of various genes expressions." (PMID 36171250, 2022).
hereditary inclusion-body myopathy (4 papers, 2018 to 2022). "Hereditary inclusion body myopathy (hIBM) with frontotemporal degeneration (IBMPFD) models due to mutations in VCP have been used." (PMID 36237625, 2022).
lymph node metastasis (4 papers, 2014 to 2025). "Elevated VCP/p97 levels have been linked to lymph node metastasis in follicular thyroid, esophageal, gastric, pancreatic and breast carcinoma." (PMID 41357812, 2025). "A multivariate analysis revealed that VCP/p97 levels, lymph node metastasis, and pT (TNM) were independent factors predicting overall survival." (PMID 34576340, 2021). "This current study also revealed that amplification of 9p was significantly associated with lymph node metastasis that might be driven by proto-oncogenes such as CA9, VCP, DCTN3, and STOML2." (PMID 28384287, 2017). "Although lymph node metastasis are more often seen in VCP-expression level 2–3, a significant correlation between high VCP-expression rate in HPV-positive and HPV-negative OSCC and lymph node metastasis could not be shown in our study." (PMID 25463965, 2014).
vacuolar myopathy (4 papers, 2015 to 2024). "VCP‐MSP was the most common disorder; rimmed vacuolar myopathy was the most frequent manifestation; distal‐predominant weakness occurred frequently in non‐VCP‐MSP; and cardiac involvement was observed only in VCP‐MSP." (PMID 36861178, 2023).
autosomal dominant retinitis pigmentosa (3 papers, 2021 to 2025). Autosomal dominant retinitis pigmentosa (RP) is an autosomally dominant inherited retinal dystrophy leading to progressive loss of the photoreceptors and retinal pigment epithelium and resulting in blindness usually after several decades. "In animal models for autosomal dominant Retinitis pigmentosa due to mutations in the RHO gene, recent preclinical findings indicate that treating imbalanced proteostasis by pharmacological inhibition of the VCP/proteasome rescues photoreceptor degeneration." (PMID 40103630, 2025). "We used magnetic nanoparticles (MNPs) and magnetic force (Reverse Magnetofection) to deliver siRNA/MNP complexes into retinal explant tissue, targeting valosin-containing protein (VCP) previously established as a potential therapeutic target for autosomal dominant retinitis pigmentosa (adRP)." (PMID 33562020, 2021).
colon cancer (3 papers, 2012 to 2021). "In colon cancer, the cytotoxicity of NMS-873 was suppressed by a VCP mutation located in the D2 domain (Ala530Thr) in NMS-873-resistant HTC116 cell lines." (PMID 34576340, 2021). "Another group reported, in 2012, that serum VCP/p97 levels were elevated in patients with colon cancer." (PMID 34576340, 2021). "Very recently, the complex between VCP/p97 and ubiquitin-specific protease 11 (USP11) was verified to influence VCP/p97 expression and colon cancer-drug resistance in HTC116 colon cancer cells." (PMID 34576340, 2021). "Moreover, VCP/p97 knockdown inhibits cell proliferation, chemoresistance and invasion and induces apoptosis in HCT116 colon cancer cells, whereas its overexpression suppresses apoptosis and chemoresponsiveness and promotes the proliferation and invasion of RKO colon cancer cells." (PMID 34576340, 2021).
COVID-19 (3 papers, 2023 to 2025). A disease caused by infection with severe acute respiratory syndrome coronavirus 2. "Inhibition of the AAA ATPase p97/VCP with CB-5083, UPCDC-30245, or NMS-873 also significantly reduced viral infection, indicating that the ER-associated protein degradation (ERAD) pathway may serve as a potential target for the treatment of COVID-19." (PMID 40540531, 2025).
diabetes (3 papers, 2021 to 2025). "DICAR expression is decreased and the effect of VCP on the degradation of the ubiquitinated protein is thus enhanced in diabetes." (PMID 36882410, 2023). "In a recent paper, VCP/p97 was identified as a hub gene that plays an important role in the association between HCC and type 2 diabetes mellitus using bioinformatics approaches." (PMID 34576340, 2021). "AGEs could downregulate DICAR, which in turn promoted the VCP function in the development of cardiac pyroptosis in diabetes." (PMID 36882410, 2023).
diabetic cardiomyopathy (3 papers, 2021 to 2025). Diabetic cardiomyopathy is a disorder of the heart muscle in people with diabetes. "For instance, circRNA DICAR has been found to inhibit cardiomyocyte apoptosis by binding to Valosin-containing protein (VCP) in diabetic cardiomyopathy, and exercise interventions can upregulate its expression to counteract metabolic dysfunction." (PMID 40710772, 2025). "In particular, the role of VCP/p97 in protection against non-ischemic heart disease, including diabetic cardiomyopathy and idiopathic dilated cardiomyopathy should be elucidated." (PMID 33439255, 2021). "Moreover, elucidating VCP/p97’s role in safeguarding against non-ischemic heart conditions, including diabetic cardiomyopathies and idiopathic dilated cardiomyopathies, is imperative." (PMID 38069058, 2023).
distal myopathy (3 papers, 2016 to 2024). Distal myopathy refers to a group of muscle diseases which share the clinical pattern of predominant weakness and atrophy beginning in the feet and/or hands. "They share defective autophagy as common feature and include hereditary diseases, such as Pompe disease, Danon disease or X-linked myopathy with excessive autophagy and very rare disorders such as valosin-containing protein (VCP)-associated myopathy or matrin-3-related distal myopathy." (PMID 38214778, 2024). "Furthermore, a distinct form of distal myopathy can arise from mutations in VCP." (PMID 32823799, 2020). "However, the functional abrogation caused by the specific mutation leading to VCP-associated distal myopathy have not been studied in detail." (PMID 32823799, 2020).
esophageal squamous cell carcinoma (3 papers, 2014 to 2021). Esophageal squamous cell carcinoma (ESCC) is a type of esophageal carcinoma (EC) that can affect any part of the esophagus, but is usually located in the upper or middle third. "Additionally, patients with esophageal squamous cell carcinoma (ESCC) present higher VCP/p97 expression, which is significantly correlated with higher frequencies of lymph node metastasis, deep invasion (pT3 and pT4), local recurrence and distant metastasis." (PMID 34576340, 2021).
Ewing sarcoma (3 papers, 2020 to 2024). A small round cell tumor that lacks morphologic, immunohistochemical, and electron microscopic evidence of neuroectodermal differentiation. "VCP/p97 is also a substrate of protein tyrosine phosphatase L1 (PTPL1), and tyrosine phosphorylation promotes the tumorigenesis of Ewing sarcoma cells." (PMID 34576340, 2021). "As VCP/p97 phosphorylation is necessary for PTPN13 midbody localization during cell division, a PTPN13 pro-oncogenic role in Ewing sarcoma, mediated through regulation of cell division, could be suggested." (PMID 33322542, 2020). "Controls (two Ewing sarcomas, two clear cell sarcomas) had no TFE3 and scant nuclear VCP immunofluorescence." (PMID 38326311, 2024).
glioblastoma (3 papers, 2019 to 2022). The most malignant astrocytic tumor (WHO grade IV). "We then tested whether suboptimal nutrient availability would alter VCP/p97 expression and observed that glutamine depletion upregulated VCP/p97 mRNA in A549, DU145, and A172 (glioblastoma) cells." (PMID 30626938, 2019).
HCMV infection (3 papers, 2017 to 2021). "If knockdown of VCP disrupts the DNA damage response during HCMV infection, this could contribute to the observed loss of IE2 expression and inhibition of virus replication." (PMID 28494016, 2017). "Although VCP has been shown to have a role in RNA processing, its mechanism of action during HCMV infection remains to be determined." (PMID 34578461, 2021). "While VCP plays a role in US11-specific degradation of MHC class I protein during HCMV infection a direct role for VCP in the replication of HCMV has not previously been reported." (PMID 28494016, 2017). "VCP displayed dynamic temporal cellular localisation during HCMV infection." (PMID 28494016, 2017). "Finally, we show that NMS-873, a small molecule inhibitor of VCP, is a potent HCMV antiviral with potential as a novel host targeting therapeutic for HCMV infection." (PMID 28494016, 2017).
leukemia (3 papers, 2008 to 2024). A malignant (clonal) hematologic disorder, involving hematopoietic stem cells and characterized by the presence of primitive or atypical myeloid or lymphoid cells in the bone marrow and the blood. "Most importantly, as the identification of menin as a co-factor for MLL fusions did for leukemias, VCP identified as a co-factor for the AT3 fusion oncoprotein will immediately widen the avenues of investigation into both biology and therapy for ASPS and Xp11-rearranged RCC." (PMID 38326311, 2024).
lymphoma (3 papers, 2015 to 2024). A malignant (clonal) proliferation of B- lymphocytes or T- lymphocytes which involves the lymph nodes, bone marrow and/or extranodal sites. "In a study conducted with lymphoma cell lines, after transfection with p97/VCP, siRNA supported the apoptosis of cells." (PMID 39473740, 2024). "We further demonstrate that pharmacological inhibition of VCP results in preferential lymphoma cell kill over PBMCs, validating VCP as a therapeutic target." (PMID 26104798, 2015). "VCP expression levels in canine lymphoma cell lines were also analyzed by immunoblotting and compared to PBMCs." (PMID 26104798, 2015). "The aim of the present study was to evaluate VCP as a therapeutic target for lymphoma using the canine model." (PMID 26104798, 2015). "The selective activity of EER-1 against lymphoma cells suggests that VCP will represent a clinically useful therapeutic target for the treatment of lymphoma." (PMID 26104798, 2015). "This is supported by the documented overexpression of VCP in many cancers including lymphoma, and often in a manner correlating with malignancy and poor outcome." (PMID 26104798, 2015). "VCP expression was found to be to be higher in all lymphomas cell lines compared to PBMCs." (PMID 26104798, 2015). "VCP expression in canine lymphomas was evaluated by immunoblotting and immunohistochemistry." (PMID 26104798, 2015).
lysosomal storage disease (3 papers, 2022 to 2024). A metabolic disorder caused by mutations in proteins critical for lysosomal function, including lysosomal enzymes, lysosomal integral membrane proteins, and proteins involved in the post-translational modification and trafficking of lysosomal proteins. "We found that VCP mutants induce the formation of aberrant multilamellar organelles in VCP animal and cell models similar to those found in patients with VCP mutations or with lysosomal storage disorders." (PMID 35501124, 2022). "Lysosomes hold potential as an attractive target for therapeutic intervention in ALS, as in addition to VCP, several other ALS associated genes have a role in lysosomal homeostasis (C9orf72, TARDBP, TMEM106B, TBK1, OPTN, SQSTM1) and several lysosomal storage diseases manifest neurological features." (PMID 39593143, 2024). "Similarly to OPTN and SQSTM1, also VCP and PFN1 share common roles in autophagic degradation raising the hypothesis of a common pathogenic mechanism affecting the formation and clearance of misfolded proteins in PDB, ALS and, more generally, in lysosomal storage diseases." (PMID 36035996, 2022).
muscular dystrophy (3 papers, 2020 to 2021). Muscular dystrophy (MD) refers to a group of more than 30 genetic diseases characterized by progressive weakness and degeneration of the skeletal muscles that control movement. "Of note, the proteins encoded by genes linked to other muscular dystrophies such as COL6A1, CAV3, DYSF, DMD, TTN, and VCP and the strongest family sequencing candidates INTS1 and ANK2 were all found in nuclear envelope proteomics datasets." (PMID 31862442, 2020).
myocardial infarction (3 papers, 2021 to 2023). Gross necrosis of the myocardium, as a result of interruption of the blood supply to the area, as in coronary thrombosis. "VCP/p97 plays a protective role in ischemia/reperfusion injuries, as evidenced by a 50% reduction in myocardial infarction size in VCP/p97 transgenic mice compared to their wild-type counterparts following ischemia/reperfusion events." (PMID 38069058, 2023). "VCP/p97 is a protective factor in ischemia/reperfusion injury, supported by a 50% reduction in the myocardial infarction area in VCP/p97 transgenic mice compared with that in wild-type mice after ischemia/reperfusion injury." (PMID 33439255, 2021). "A new substance (KUS121), which inhibits the ATPase activity of VCP/p97, has been shown to exert protective effects in in vivo myocardial infarction models, and in in vitro cardiomyocyte hypoxia models, which is contradictory to a study involving VCP/p97 K524A transgenic mice." (PMID 33439255, 2021).
neuropathy (3 papers, 2017 to 2025). A disorder affecting the nervous system that manifests with pain, tingling, numbness, and/or muscle weakness. "Damaged lysosomes accumulate in cells expressing mutant VCP showing that its role in clearing out damaged lysosomes is compromised by neuropathy- causing mutations." (PMID 28553203, 2017). "This function of VCP in maturation of autophagosomes seems to be impaired by neuropathy-causing mutations." (PMID 28553203, 2017). "Some multi-gene panels for myopathy, skeletal disorders, dementia, ALS, spastic paraplegia, neuropathy, and PD, include the VCP gene." (PMID 35093159, 2022). "Mutations in VCP cause a multisystem degenerative disease consisting of inclusion body myopathy, Paget’s diseases and frontotemporal dementia (IBMPFD), familial ALS and can also lead to CMT2Y neuropathy with distal muscle weakness and atrophy and length-dependent sensory loss." (PMID 28553203, 2017).
oral cancer (3 papers, 2014 to 2021). "In parallel, another oral cancer cell line (Cal-27) overexpressing VCP/p97 presented a significant increase in cell proliferation, the number of colonies formed in soft agar and colony size." (PMID 34576340, 2021). "The overexpression of VCP/p97 has also been detected in oral cancer, and its knockdown reduces cell proliferation and growth rates in oral cancer cells (SCC-9)." (PMID 34576340, 2021). "Of these four lines, only the amplicon in SCC-9 spanned all four oral cancer candidate genes defined by our analyses of oral cancer tissues (VCP, STOML2, and DCTN3)." (PMID 25060540, 2014). "The functional significance of VCP, STOML2, and DCTN3 in oral cancer phenotypes was evaluated by shRNA-mediated knockdown experiments using oral cancer cell line SCC-9." (PMID 25060540, 2014). "Within this region, VCP, STOML2, and DCTN3 were identified as candidate oncogenes and we demonstrate that each is able to regulate oral cancer phenotypes." (PMID 25060540, 2014).
oropharyngeal squamous cell carcinoma (3 papers, 2014 to 2021). "VCP/p97 expression has also been determined in patients with oropharyngeal squamous cell carcinoma (OSCC) using immunohistochemistry, and its putative correlation with HPV-DNA has been analyzed." (PMID 34576340, 2021). "VCP is located on chromosome 9p13-p12, a region often deleted in oropharyngeal squamous cell carcinoma (OSCC)." (PMID 25463965, 2014). "Indeed, we have been previously reported that the low expression of SLC7A11 predicted short OS as well as DFS in a smaller cohort of 489 OC patients; and low levels of VCP in HPV-negative patients was related to worse 5-year DFS in oropharyngeal squamous cell carcinoma." (PMID 34790572, 2021).
renal cell carcinoma (3 papers, 2021 to 2026). "As a result, five aging-related genes (DUSP22, MAPK14, MAPKAPK3, STAT1, and VCP) in normal tissues were found to be significantly associated with a worse survival outcome in patients with renal cell carcinoma (RCC)." (PMID 34207247, 2021).
Spastic paraplegia (3 papers, 2022). Complete loss of the ability to move the lower limbs accompanied by spasticity of the lower limbs. "Because of this, the diagnosis of VCP-MSP is best achieved by the inclusion of VCP in numerous sequencing panels including myopathy, PDB, FTD, ALS, axonal Charcot-Marie-Tooth disease, and/or spastic paraplegia." (PMID 35741724, 2022).
triple-negative breast carcinoma (3 papers, 2021 to 2025). An invasive breast carcinoma which is negative for expression of estrogen receptor (ER), progesterone receptor (PR), and human epidermal growth factor receptor 2 (HER2). "Notably, pharmacological inhibition of valosin containing protein (VCP) or depleting Derlin‐1 in mice reduces TMEM63A‐mediated triple negative breast cancer progression and metastasis." (PMID 41015904, 2025).
acute lymphoblastic leukemia (2 papers, 2021 to 2022). Leukemia with an acute onset, characterized by the presence of lymphoblasts in the bone marrow and the peripheral blood. "Inhibition of VCP has been tested in diverse cancer cell lines and tumor models: CB-5083 has been suggested to decrease cell growth in MM, acute lymphoblastic leukemia (ALL), and lymphoma." (PMID 35385564, 2022). "Furthermore, higher levels of VCP/p97 were identified in poor vs. good prednisone responders by analyzing leukemic blasts in patients with childhood acute lymphoblastic leukemia (ALL)." (PMID 34576340, 2021).
Ataxia (2 papers, 2016 to 2020). Ataxia refers to impaired coordination of voluntary muscle movement. "Therefore, we can assume that changes in the amino acid structure of ITPR1 may indirectly affect the activity of VCP or ATXN3, which may contribute to the development of a neurodegenerative process in this type of ataxia." (PMID 26770814, 2016).